MACC1 (MET transcriptional regulator MACC1)
Description:
Acts as a transcription activator for MET and as a key regulator of HGF-MET signaling. Promotes cell motility, proliferation and hepatocyte growth factor (HGF)-dependent scattering in vitro and tumor growth and metastasis in vivo.
Synonyms: 7A5; SH3BP4L
Tractability: No criterion of Open Targets' tractability assessment is met for any kind of drug.
Gene: Protein-coding gene on chromosome 7 (20,134,655 to 20,217,457, reverse strand). Ensembl gene ENSG00000183742.
Subcellular location: Cytoplasm; Nucleus
Subcellular location (Human Protein Atlas): Mitochondria
Gene Ontology:
Biological process: positive regulation of transcription by RNA polymerase II
Cellular component: cytoplasm; nucleus
Genetic constraint (gnomAD): Loss-of-function variants: 75 observed, 69.98 expected, observed/expected ratio (o/e) 1.07, 90% interval 0.89 to 1.3. The upper end of that interval is the gene's LOEUF score, 1.3, which puts it in group 5 of 6, group 1 being the genes least tolerant of losing a copy. Missense variants: 1,082 observed, 1,009.2 expected, observed/expected ratio (o/e) 1.07, 90% interval 1.02 to 1.13. Synonymous variants: 357 observed, 358.36 expected, observed/expected ratio (o/e) 1, 90% interval 0.91 to 1.09.
Cancer hallmarks: angiogenesis (promotes); invasion and metastasis (promotes); escaping programmed cell death (promotes)
Homologues: Orthologues: chimpanzee MACC1 (99% identical), macaque MACC1 (93% identical), dog MACC1 (82% identical), pig MACC1 (82% identical), guinea pig MACC1 (82% identical), rabbit MACC1 (79% identical), mouse Macc1 (77% identical), rat Macc1 (76% identical), tropical clawed frog macc1 (60% identical), zebrafish macc1 (45% identical). Paralogues in human: SH3BP4 (42% identical).
Diseases named in the same sentence as MACC1 in open-access papers:
MACC1 is named in the same sentence as 121 diseases in open-access papers, as found by Europe PMC text mining. Sharing a sentence is not in itself a finding about the gene and the disease. The quoted sentences say what the papers report.
colorectal cancer (98 papers, 2012 to 2026). A primary or metastatic malignant neoplasm that affects the colon or rectum. "MACC1 is also linked to epithelial to mesenchymal transition and is considered a poor prognosis marker in colorectal cancer." (PMID 39859345, 2025). "A saffron extract had positive effects on colorectal cancer stem cells by down-regulating metastasis associated with colon cancer 1 (MACC1)." (PMID 39859345, 2025). "Patients with colorectal cancer who have the MACC1 SNP rs1990172 G allele have a significantly lower overall survival rate." (PMID 36979146, 2023). "In 2009, the gene metastasis associated in colon cancer 1 (MACC1) was discovered in colorectal cancer and connected to increased metastasis, cell survival, proliferation, and migration." (PMID 37051546, 2023). "When MACC1 was first associated with colorectal cancer, it was discovered that the HGF/c-Met signaling pathway played a role in its ability to promote cancer." (PMID 36979146, 2023). "High expression of MACC1 protein in colorectal cancer or high MACC1 transcripts in the blood are strongly associated with advanced disease with metastasis, making it a potentially useful biomarker." (PMID 37496665, 2023). "Gain- and loss-of-functions performed in vitro revealed that MACC1 acts as an oncogene in multiple human tumors, such as colorectal cancer, breast cancer, gastric cancer, and ovarian cancer." (PMID 34939526, 2022). "High metastasis-associated in colon cancer 1 (MACC1) expression is associated with metastasis, tumor cell migration, and increased proliferation in colorectal cancer." (PMID 35740524, 2022). "MACC1 (metastasis-associated in colon cancer 1) was demonstrated to expresses differently in human colorectal cancer tissues in a genome-wide search." (PMID 34939526, 2022). "In 2009, we identified the gene MACC1 (Metastasis Associated in Colon Cancer 1) in human colorectal cancer." (PMID 35406545, 2022). "In a wide range of solid tumor types, notably colorectal cancer, MACC1 (Metastasis Associated in Colon Cancer 1) is a critical regulator and predictive biomarker for colorectal cancer growth and metastasis." (PMID 36080453, 2022). "In colorectal cancer cells, treatment with adalimumab hindered the induction of the Metastasis-Associated in Colon Cancer 1 (MACC1), a crucial oncogene that promotes cell proliferation, motility, and survival, increasing metastasis in preclinical models." (PMID 33540543, 2021). "Metastasis Associated in Colon Cancer 1 (MACC1) is a novel prognostic, predictive and causal biomarker for tumor progression and metastasis in many cancer types, including colorectal cancer." (PMID 33469705, 2021). "Confirming the results in colorectal cancer, MACC1 expression is associated with a worse prognosis in various solid tumor types, including GBM." (PMID 32503676, 2020). "In summary, our findings indicated that MACC1 is a valuable prognostic and risk stratification biomarker for colorectal cancer patients." (PMID 30805302, 2019). "In colorectal cancer cells, miR-218-5p reduced migration, invasion and colony formation by targeting the Metastasis Associated with Colon Cancer 1 protein (MACC1)." (PMID 29899866, 2018). "Other determinants of invasion are components and modulators of the HGF/c-Met pathway, such as metadherin in breast cancer and the metastasis-associated in colon cancer 1 (MACC1) gene in colorectal carcinoma." (PMID 29455657, 2018). "Several biomarkers and mutations of aggressive tumor behavior have been defined such as metastasis-associated in colon cancer 1 (MACC1) that was associated with metastasis in colorectal cancer patients." (PMID 27439755, 2016).
colorectal cancer (continued). "Metastasis associated in colon cancer 1 (MACC1) was identified through differential display RT-PCR analysis of normal colon mucosa, colorectal cancer (CRC) and respective metastasis tissue specimens in our group." (PMID 27462788, 2016). "Metastasis-associated in colon cancer-1 (MACC1), a newly identified gene first detected in colorectal cancer, is suggested to transcriptionally regulate c-Met." (PMID 27793048, 2016). "Metastasis-associated in colon cancer-1 (MACC1) promotes colorectal cancer progression and predicts prognosis." (PMID 27793048, 2016). "Metastasis-associate in colon cancer-1 (MACC1) has been identified as a metastatic and prognostic biomarker for colorectal cancer and other solid tumors." (PMID 27832750, 2016). "The metastasis-associated in colon cancer 1 (MACC1) gene has been identified as prognostic biomarker for colorectal cancer (CRC)." (PMID 25742883, 2015). "Metastasis-associated in colon cancer 1 (MACC-1) is recently discovered as an extremely important metastasis-related gene to regulate the metastasis of colorectal cancer as well as a variety of other solid tumors." (PMID 24936152, 2014). "The aim of this study was to investigate the relationship of MACC-1 (metastasis-associated in colon cancer 1) and microRNA (miRNA) hsa-miR-574-5p and the function of hsa-miR-574-5p in colorectal cancer liver metastasis." (PMID 24936152, 2014). "Previous reports have showed that overexpression of MACC1 potentiates metastasis and recurrence of colorectal cancer, and associates with peritoneal dissemination and higher stage of TNM classification in colorectal carcinomas." (PMID 23573286, 2013). "Metastasis-associated in colon cancer-1 (MACC1) has been newly identified to express highly in colorectal cancer (CRC) and promote tumor metastasis through transactivating metastasis-inducing HGF/MET signaling pathway." (PMID 22533346, 2012). "We therefore investigated the association between MACC1 tagging SNPs capturing the majority of common alleles at the MACC1 locus and overall survival in a large cohort of colorectal cancer patients." (PMID 22251819, 2012). "For the first time, our study investigated the influence of MACC1 tagging polymorphisms on overall survival suggesting SNP rs1990172 as a predictor for reduced overall survival in colorectal cancer patients." (PMID 22251819, 2012). "MACC1 is a prognostic marker for distant metastasis formation and allows the identification of colorectal cancer patients with a high risk for metastatic cancer." (PMID 22838389, 2012). "Our study provides the first results that the genetic diversity of the MACC1 locus is associated with overall survival in colorectal cancer patients." (PMID 22251819, 2012). "We therefore investigated the association between MACC1 tagging single nucleotide polymorphisms (SNPs) and overall survival in a large cohort of colorectal cancer patients." (PMID 22251819, 2012). "Here, we analyzed for the first time the impact of single nucleotide polymorphisms (SNPs) in the coding region of MACC1 for clinical outcome of colorectal cancer patients." (PMID 22838389, 2012). "Elevated metastasis-associated in colon cancer 1 (MACC1) expression in colorectal cancer patients, and high transmembrane 4 L6 family member 5 (TM4SF5) protein expressed on various solid tumors’ surface, are linked to aggressive cancer behavior and progression." (PMID 39273182, 2024). "In addition, colorectal cancer has been shown to be upregulated by transcription factors such as metastasis-associated in colon cancer protein 1 (MACC1) or early growth response protein 1 (EGR1), which are involved in angiogenesis and metastasis." (PMID 32492954, 2020). "TTP has been shown to directly regulate EMT regulators, including ZEB1 (zinc finger E-box binding homeobox 1), SOX9 (sex-determining region Y box 9), and MACC1 (metastasis associated in colon cancer 1), all of which are known to be downregulated in colorectal carcinomas (CRC)." (PMID 32545247, 2020).
colorectal cancer (continued). "Association between MACC1 status with clinicopathological parameters in colorectal cancer patients." (PMID 30805302, 2019). "Summary, plasma MACC1 levels could be a useful prognostic and diagnostic biomarker, and could improve the prognostic value of traditional prognosticators for colorectal cancer patients." (PMID 30370603, 2019). "Recent research has suggested that SPON2 mediates metastasis-associated in colon cancer 1 (MACC1)–induced colorectal cancer proliferation, invasion, and metastasis in vitro and in vivo, while aberrant overexpression of SPON2 increases adverse disease-free survival in clinical samples." (PMID 28938639, 2017). "MACC1 (Metastasis Associated in Colon Cancer 1) is a key driver and prognostic biomarker for cancer progression and metastasis in a large variety of solid tumor types, particularly colorectal cancer (CRC)." (PMID 28570591, 2017). "Metastasis-associated in colon cancer 1 (MACC1) was initially shown to promote the metastatic capacities of colorectal cancer, and clinical studies have indicated that it may be an independent prognostic indicator of recurrence and disease-free survival (DFS)." (PMID 25009663, 2014). "The aim of this study was to investigate the relationship between multiple metabolism parameters derived from FDG and tumor TNM stages as well as tumor metastasis-associated protein of GLUT-1 and MACC1 in colorectal carcinoma (CRC)." (PMID 33750337, 2021). "GIPC1 has dual functions in the progression and metastasis of MACC1-driven primary colorectal cancer." (PMID 41522336, 2026). "MACC1 is abnormally increased in solid tumors such as colorectal cancer, pancreatic cancer and breast cancer 39-41." (PMID 40740230, 2025). "It promotes platelet-mediated cancer cell communication, particularly in MACC1-driven colorectal cancer metastasis." (PMID 41226816, 2025). "COX19, a target gene of MACC1, regulates mitochondrial activity and drives tumour progression in colorectal cancer." (PMID 40391581, 2025). "Previous work showed that CCN1 and MACC1 cooperate to promote human colorectal cancer cell metastasis, adhesion, migration, differentiation, angiogenesis, and survival." (PMID 38396744, 2024). "Interventional approaches targeting MACC1 would potentially improve further targeted therapies for colorectal cancer patients to eradicate CSCs and prevent cancer recurrence and distant metastasis formation." (PMID 38339354, 2024). "Knockdowns of MACC1 can facilitate cell death via the PI3K/Akt pathway in 5-FU-resistant colorectal cancer." (PMID 39062099, 2024). "Our findings showed a novel mechanism, underlying the antimetastatic activity of parecoxib in colorectal cancer by inhibiting p-Akt, p-ERK, p-GSK3β, MACC1, and cMet to induce the inhibition of epithelial–mesenchymal transition (EMT) and β-catenin." (PMID 39062099, 2024). "In colorectal cancer, MACC1 expression was connected to increased S100A4 secretion, induced by the β-catenin/TCF4 axis." (PMID 37051546, 2023). "In colorectal cancer, a core promoter region (−426 to −18) of the MACC1 gene is essential for transcriptional activity." (PMID 37664587, 2023). "This is the first study which analyses the translation of pharmacological MACC1 inhibition for another tumor entity, extending our knowledge focused on colorectal cancer." (PMID 35406545, 2022). "We found that, under the regulation of the MACC1/HGF/c-MET axis, the proliferation and metastasis of colorectal cancer are increased by MACC1, which can be a novel biomarker for predicting ICIs response in colorectal cancer." (PMID 35874635, 2022). "Most significantly, lovastatin and rottlerin inhibited MACC1 expression and liver metastases in colorectal cancer-xenografted mice." (PMID 36080453, 2022).
colorectal cancer (continued). "Recently, we showed that MEK1 directly phosphorylates MACC1, leading to activation of MACC1-induced migration and metastasis in colorectal cancer." (PMID 35406545, 2022). "MiR-944 inhibits colorectal cancer cell migration as well as invasion by targeting MACC1 (MET transcriptional regulator MACC1)." (PMID 35365168, 2022). "Recent studies have reported that S100P is a new target gene of MACC1 that drives colorectal cancer metastasis and serves as a prognostic biomarker." (PMID 36276281, 2022). "Detection of high levels of MACC1 transcripts in colorectal cancer tumor tissue or blood samples is predictive for metastasis formation and shorter overall survival." (PMID 35406545, 2022). "Metastasis-associated in colon cancer 1 (MACC1) is a marker for metastasis, tumor cell migration, and increased proliferation in colorectal cancer (CRC)." (PMID 35740524, 2022). "Beside colorectal cancer, MACC1 has been confirmed as a prognostic biomarker in a variety of other solid cancers such as pancreatic, hepatocellular/biliary, lung, ovarian, breast, renal, bladder, nasopharyngeal cancer, glioblastoma, and osteosarcoma." (PMID 35406545, 2022). "The context of copy number gain and overexpression of MACC1 was also analyzed by Galimi and colleagues in a cohort of 103 consecutive metastasized colorectal carcinomas." (PMID 35406521, 2022). "MACC1 gene is a newly discovered gene and plays an important role in the metastasis of colorectal cancer (CRC)." (PMID 34343214, 2021). "MACC1 is an oncogene involved in molecular pathogenesis of colorectal cancer (CRC) and other solid tumor entities, mediating motility and metastasis, making MACC1 an accepted prognostic biomarker." (PMID 34830078, 2021). "In colorectal cancer, miR-338-3p can down-regulate MACC1 expression to suppress cancer cell growth, migration and invasion." (PMID 34889689, 2021). "Recently, there are several reports on the relationship between MACC1 SNPs and cancers, such as colorectal cancer, hepatocellular carcinoma, and breast cancer." (PMID 34072650, 2021). "Studies have shown that knockout MACC1 significantly inhibits proliferation, migration, invasion and tumorigenesis of colorectal cancer cells, and induces apoptosis." (PMID 33712897, 2021). "In colorectal cancer, miR-338-3p targets MACC1 to modulate tumor cells proliferation, migration, and apoptosis." (PMID 34718336, 2021). "This indicates that the stronger the cell's ability to metastasize, the higher its MACC1 expression, and MACC1 can also reflect the metastatic ability of colorectal cancer cells." (PMID 33712897, 2021). "The lnc-HSD17B11-1:1 was found to promote colorectal cancer progression through the lnc-HSD17B11-1:1/miR-338-3p/MACC1 axis." (PMID 34101736, 2021). "Metastasis-associated in colon cancer 1 (MACC1) and Spondin2 (SPON2) are newly discovered oncogenes, but little is known about their role in colorectal cancer(CRC) liver metastases." (PMID 33712897, 2021). "MACC1 was first identified in 2009 as a prognostic biomarker for metastasis formation in colorectal cancer." (PMID 32503676, 2020). "The 5 years survival rate for patients with high MACC1 expression in the primary colorectal cancer has been identified to be only 15% as compared to 80% for those with low MACC1 expression." (PMID 32174779, 2020). "Here we report the MACC1 dependent treatment resistance of colorectal cancer (CRC) cells to standard therapeutics like doxorubicin by upregulating ATP-binding cassette subfamily B member 1 (ABCB1) protein." (PMID 32391276, 2020). "In colorectal cancer, MACC1 SNP rs1990172 was suggested as a predictor for reduced overall survival in colorectal cancer patients." (PMID 32047570, 2020). "The mechanism includes hsa-miR-574-5p negatively regulating MACC-1 expression to reach suppression in colorectal cancer." (PMID 32832554, 2020).